LINC01271 (long independently transcribed non-coding RNA 1271)
Gene: Long non-coding RNA gene on chromosome 20 (50,299,081 to 50,321,486, reverse strand). Ensembl gene ENSG00000233077.
Diseases named in the same sentence as LINC01271 in open-access papers:
LINC01271 is named in the same sentence as 4 diseases in open-access papers, as found by Europe PMC text mining. Sharing a sentence is not in itself a finding about the gene and the disease. The quoted sentences say what the papers report.
breast carcinoma (1 paper, 2020). "Ultimately, LINC01271 is an ideal candidate to be exploited as a potential prognostic/therapeutic target and LINC01271-specific ASOs as therapeutics to impact breast cancer progression and metastasis." (PMID 33353933, 2020). "Together, our data reveal MaTAR25, and its identified human ortholog LINC01271, as an exciting therapeutic candidate whose expression can be altered to impede breast cancer progression and metastasis." (PMID 33353933, 2020).
breast tumors (1 paper, 2020). "We found that LINC01271 expression level was increased with increased breast tumor stage, and we identified the presence of clonal and regional differential expression patterns in most of the breast tumor patient samples." (PMID 33353933, 2020). "The human ortholog of MaTAR25 was identified as LINC01271, and it is expressed in primary breast tumors and at even higher levels in lymph node and lung metastases." (PMID 33353933, 2020). "qRT-PCR analysis of the expression level of LINC01271 in breast tumor organoids vs organoids derived from normal adjacent breast tissue showed a higher expression level of LINC01271 in tumor-derived organoids." (PMID 33353933, 2020).
glioma (1 paper, 2023). A benign or malignant brain and spinal cord tumor that arises from glial cells (astrocytes, oligodendrocytes, ependymal cells). "In conclusion, knockout of LINC01271 visibly suppressed the proliferation and migration of glioma cells, proving that LINC01271 positively regulates the progression of glioma and lncRNA LINC01271 is expected to become a new target for the treatment." (PMID 37837543, 2023). "The expression of LINC01271 is also in connection with some hallmark gene sets, such as APOPTOSIS, COAGULATION, COMPLEMENT, and E2F TARGETS, suggesting the immune pathways related to characteristic genes, and perhaps related to the mechanism of LINC01271’s biological role in glioma." (PMID 37837543, 2023). "The role of LINC01271 in gliomas has not been reported, so we selected LINC01271 as the target to investigate its impact on glioma development and prognosis." (PMID 37837543, 2023).
LINC01271 also shares sentences with these, for which no sentence is quoted: tumor (1 paper).